MIR1179 (microRNA 1179)
Synonyms: hsa-mir-1179; MIRN1179; mir-1179
Gene: MicroRNA gene on chromosome 15 (88,608,107 to 88,608,197, forward strand). Ensembl gene ENSG00000221630.
Homologues: Orthologues: chimpanzee ptr-mir-1179 (100% identical).